MUC15 (mucin 15, cell surface associated)
Description:
May play a role in the cell adhesion to the extracellular matrix.
Synonyms: MUC-15; PAS3; PASIII
Tractability: Antibody: UniProt places it where antibodies can reach, with high confidence; its Gene Ontology location is reachable by antibodies, with high confidence; UniProt predicts a signal peptide or a membrane-spanning region.
Gene: Protein-coding gene on chromosome 11 (26,559,032 to 26,572,263, reverse strand). Ensembl gene ENSG00000169550.
Subcellular location: Cell membrane (Isoform 1); Secreted (Isoform 2)
Pathways (Reactome):
Disease: Defective C1GALT1C1 causes TNPS; Defective GALNT12 causes CRCS1; Defective GALNT3 causes HFTC
Metabolism of proteins: O-linked glycosylation of mucins; Termination of O-glycan biosynthesis
Immune System: Dectin-2 family
Gene Ontology:
Molecular function: protein binding
Cellular component: Golgi lumen; plasma membrane; extracellular region
Genetic constraint (gnomAD): Loss-of-function variants: 21 observed, 22.88 expected, observed/expected ratio (o/e) 0.92, 90% interval 0.65 to 1.32. The upper end of that interval is the gene's LOEUF score, 1.32, which puts it in group 5 of 6, group 1 being the genes least tolerant of losing a copy. Missense variants: 431 observed, 428.92 expected, observed/expected ratio (o/e) 1, 90% interval 0.93 to 1.09. Synonymous variants: 146 observed, 156.67 expected, observed/expected ratio (o/e) 0.93, 90% interval 0.81 to 1.07.
Homologues: Orthologues: chimpanzee MUC15 (96% identical), macaque MUC15 (89% identical), rabbit MUC15 (67% identical), dog MUC15 (64% identical), pig MUC15 (63% identical), mouse Muc15 (55% identical), guinea pig MUC15 (52% identical), rat Muc15 (45% identical), tropical clawed frog MUC15 (26% identical), zebrafish vsig8b (13% identical), zebrafish si:dkey-22i16.9 (12% identical), zebrafish jam2b (10% identical), and 1 more. Paralogues in human: CXADR (16% identical), CLMP (14% identical), IGSF11 (13% identical), ESAM (12% identical), VSIG2 (12% identical), VSIG1 (12% identical), JAM3 (12% identical), VSIG8 (12% identical), MXRA8 (11% identical), F11R (11% identical), GPA33 (10% identical), JAM2 (9% identical), and 2 more.
Diseases named in the same sentence as MUC15 in open-access papers:
MUC15 is named in the same sentence as 42 diseases in open-access papers, as found by Europe PMC text mining. Sharing a sentence is not in itself a finding about the gene and the disease. The quoted sentences say what the papers report.
hepatocellular carcinoma (10 papers, 2016 to 2025). A malignant tumor that arises from hepatocytes. "As noted, downregulated MUC15 expression is associated with poor clinical prognosis in hepatocellular carcinoma." (PMID 40385549, 2025). "Next, we found that MUC15 overexpression downregulated the expression of liver T-ICs markers and stemness-associated transcription factors in hepatoma spheroids." (PMID 35236826, 2022). "In hepatocellular carcinomas, decreased MUC15 expression was seen and associated with more aggressive phenotypes and shorter survival." (PMID 28978023, 2017). "MUC15 was with decreased expression in hepatocellular carcinoma (HCC), and its overexpression significantly suppressed EGF induced dimerization of EGFR and activation of PI3K-AKT pathway, which finally inhibited tumor cell migration and invasion." (PMID 40225867, 2025). "The MUC15/c-Met/PI3K/AKT/SOX2 axis determines the responses of hepatoma cells to lenvatinib treatment, as supported by the observation that MUC15 overexpression abrogates lenvatinib resistance." (PMID 36980210, 2023). "MUC15 inhibits hepatoma cell self-renewal, malignant proliferation, tumorigenicity, and chemoresistance by interacting with c-Met and subsequently inactivating the PI3K/AKT/SOX2 signaling pathway." (PMID 36980210, 2023). "The sensitivity of lenvatinib in hepatoma cells was upregulated in MUC15 overexpression hepatoma cells." (PMID 35236826, 2022). "More importantly, our data demonstrated that SOX2 is required for MUC15-mediated lenvatinib response in hepatoma cells." (PMID 35236826, 2022). "Mucin 15 (MUC15) is reportedly aberrant in human malignancies, including hepatocellular carcinoma (HCC)." (PMID 35236826, 2022). "Western blot analysis further confirmed that p-AKT was downregulated in MUC15 overexpression hepatoma spheroids." (PMID 35236826, 2022). "More importantly, introduction of SOX2, AKT or c-MET alleviated lenvatinib sensitivity in MUC15 overexpression hepatoma cells." (PMID 35236826, 2022). "Conversely, SOX2 overexpression decreased the level of MUC15 and increased the levels of c-MET, p-AKT in hepatoma spheroids, which further clarify that the MUC15/c-MET/PI3K/AKT/SOX2/miR-183-5p.1 regulatory circuit in liver T-ICs." (PMID 35236826, 2022). "We observed that MUC15 overexpression sensitized hepatoma cells to undergo lenvatinib-induced cell growth inhibition and cell apoptosis." (PMID 35236826, 2022). "Functional studies reveal that MUC15 inhibits hepatoma cells self-renewal, malignant proliferation, tumorigenicity, and chemoresistance." (PMID 35236826, 2022). "Ki67 staining showed a notable increase in hepatoma cell proliferation in MUC15hep−/− mice and an evidently decrease in hepatoma cell proliferation in MUC15-TG mice compared with their WT mice." (PMID 35236826, 2022). "MUC15 mRNA and protein Levels were obviously lower in hepatocellular cancer than normal tissues, and patients with lower MUC15 had shorter overall survival and disease-free survival." (PMID 32382053, 2020). "MUC15 overexpression is significantly correlated with several types of cancers, including colon cancer, hepatocellular carcinoma, and thyroid cancer." (PMID 32175327, 2020). "MUC15 upregulation is significantly correlated with various types of cancers such as colon cancer, hepatocellular carcinoma, and especially thyroid cancer." (PMID 30420637, 2018). "MUC15, a highly glycosylated extracellular protein, has been found to be elevated in the tumor initiating cell populations in colon cancer, hepatocellular carcinoma and papillary thyroid carcinoma." (PMID 26683522, 2016). "Notably, western blot analysis found that SOX2 was also downregulated in MUC15 overexpression hepatoma spheroids." (PMID 35236826, 2022). "Importantly, MUC15/c-MET/PI3K/AKT/SOX2 axis determines the responses of hepatoma cells to lenvatinib treatment, and MUC15 overexpression abrogated lenvatinib resistance." (PMID 35236826, 2022).
hepatocellular carcinoma (continued). "Furthermore, the self-renewal ability, liver T-ICs frequency and tumorigenesis capacity in MUC15 overexpression hepatoma cells can be restored through introduction of AKT." (PMID 35236826, 2022). "Spheroid formation was attenuated in MUC15 overexpression hepatoma cells." (PMID 35236826, 2022). "In this study, we discover that MUC15 was downregulated in liver T-ICs and played an essential role in hepatoma cells self-renewal, malignant proliferation, tumorigenicity, and chemoresistance, suggesting MUC15 is a novel biomarker for liver T-ICs and a potential target for HCC therapy." (PMID 35236826, 2022). "In further study, we found that hepatoma cells from MUC15 overexpression spheroids exhibited attenuated xenografted tumor growth, tumor size, and tumor weight in vivo, suggesting the inhibitory role of MUC15 in liver T-ICs propagation and HCC progression." (PMID 35236826, 2022). "Furthermore, in vitro limited dilution assays revealed that ectopic MUC15 expression attenuated the TIC-like properties in hepatoma cells." (PMID 35236826, 2022). "However, it was also found that the expression of MUC15 decreased in hepatocellular carcinoma cells and negatively regulated metastasis of hepatocellular carcinoma." (PMID 32175327, 2020). "In hepatocellular carcinoma and trophoblast-like cells, MUC15 decrease migration capability." (PMID 30420637, 2018). "However, c-MET was reduced in MUC15 overexpression hepatoma spheroids." (PMID 35236826, 2022). "In present study, we revealed that MUC15 downregulated SOX2 to inhibits T-ICs generation and weaken TIC-like properties of hepatoma cells, thus suppressing the initiation and progression of liver cancer." (PMID 35236826, 2022). "Furthermore, western blot analysis showed that MUC15 was downregulated and c-MET, p-AKT was upregulated in SOX2 knockdown hepatoma spheroids." (PMID 35236826, 2022).
colon cancer (7 papers, 2014 to 2025). "MUC15 also encodes a membrane-bound protein, which could promote cell proliferation, cell-extracellular matrix adhesion, colony forming ability, and invasion in colon cancer cells." (PMID 32175327, 2020). "For instance, MUC15 was observed highly expressed in colorectal adenocarcinomas and the oncogenic potential of human colon cancer cells." (PMID 34539882, 2021). "Consistent with the previous reports, MUC15 indeed drives the invasive behavior of colon cancer and metastasis." (PMID 30420637, 2018). "Whereas, in case of colon cancer, MUC15 drives invasive migration through boyden chambers, thereby enhancing metastasis." (PMID 30420637, 2018). "Muc15 was previously demonstrated to promote oncogenesis in colon cancer cells in vitro and in vivo." (PMID 25380620, 2014). "While Muc15 has been shown to play a key role in increasing invasiveness and tumorigenic capacity in colon cancer, it has not been linked to BC." (PMID 25380620, 2014).
thyroid cancer (5 papers, 2018 to 2025). "The present findings may provide novel insights into the development of diagnostic, prognostic, and therapeutic applications of MUC15 in thyroid cancer." (PMID 30420637, 2018). "According to previous reports and TCGA database, MUC15 (MUCIN 15) upregulation is highly correlated with thyroid cancer progression." (PMID 30420637, 2018). "We identified MUC15 plays a key role in the progression of tumorgenesis by enhancing cancer stemness in thyroid cancer." (PMID 30420637, 2018). "Consistent with reverse transcription PCR (RT-PCR) results, western blot as well as and immuno-fluorescence analyses confirmed increased MUC15 expression in thyroid cancer cells." (PMID 30420637, 2018). "To clarify the role of MUC15 in thyroid cancer progression, we first examined MUC15 expression in thyroid cancer cells (FTC-238 and TPC-1), relative to that of normal thyroid cells (Nthy-ori-3-1)." (PMID 30420637, 2018). "While investigating the physiological role of MUC15 in thyroid cancer, we found that FTC-238 cancer cells display greater sphere formation abilities; however, Nthy-ori-3-1 and TPC-1 cells did not adequately generate spheres." (PMID 30420637, 2018). "We found that one isoform of mucins, MUC15 play a critical role of mediating cancer stemness in thyroid cancers." (PMID 30420637, 2018). "In thyroid cancer, tumor progression was highly correlated with the up-regualtion of MUC15." (PMID 40225867, 2025). "MUC15-mediated signaling pathway contributes a key characteristic of CSC and confers opportunities to development novel therapeutic strategies and diagnostic/prognostic markers for thyroid cancer patients." (PMID 30420637, 2018). "Collectively, our results suggest that MUC15 play an important role in developing CSC thereby mediate metastasis and recurrence of thyroid cancer." (PMID 30420637, 2018). "Further investigation of MUC15-mediated gene expression and downstream signaling pathway will elucidate self-renewal properties of CSC for highly tumorigenic population of CSC in thyroid cancer." (PMID 30420637, 2018).
breast carcinoma (4 papers, 2021 to 2025). "MUC1 expression in breast cancer tissues was higher than that in normal breast tissues while MUC15, MUC14 and MUC18 were downregulated in cancer samples compared with normal controls." (PMID 34828282, 2021). "Breast cancer patients with higher expression of MUC1 and MUC14 but with lower expression of MUC15 and MUC18 had better OS." (PMID 34828282, 2021). "Considering the expression change of MUC1, MUC15, MUC14 and MUC18 in breast cancer, we intended to ascertain if they possessed promising predictive roles for diagnosis and prognosis of breast cancer." (PMID 34828282, 2021). "Taken together, MUC1, MUC15, MUC14 and MUC18 were identified as the most potential MUC members in breast cancer and were selected for subsequent analysis." (PMID 34828282, 2021). "Next, Kaplan-Meier plotter was employed to assess the prognostic roles of MUC1, MUC15, MUC14 and MUC18 in breast cancer." (PMID 34828282, 2021). "In accordance with OS analysis, breast cancer patients with increased expression of MUC1 and MUC14 but decreased expression of MUC15 and MUC18 possessed favorable RFS." (PMID 34828282, 2021). "However, no related protein expression data of MUC15 and MUC14 in breast cancer were obtained." (PMID 34828282, 2021).
glioma (4 papers, 2016 to 2025). A benign or malignant brain and spinal cord tumor that arises from glial cells (astrocytes, oligodendrocytes, ependymal cells). "Specific mucins that have now been implicated in glioma include MUC1, MUC4, MUC15, MUC16, MUC17, MUC18 and MUC21." (PMID 39767713, 2024). "MUC15 has also benefited from exploration in glioma and was found to mediate signal transduction." (PMID 39767713, 2024). "However, a reverse trend is seen in glioma, where increased MUC15 correlates positively with progression and stage and serves as an independent factor for prognosis." (PMID 28978023, 2017). "Work conducted by Cheng and Liu led to the finding that MUC15 activates the Raf/MEK/ERK signaling pathway, and specific ERK inhibitors reversed MUC-15’s enhanced proliferation and invasion of glioma cells, which indicates that MUC15 may have a significant role in glioma tumorigenesis." (PMID 39767713, 2024). "While MUC1, MUC4, MUC15, MUC16, MUC17, and MUC21 are all potential candidate biomarkers for glioma, the extensive research on MUC1 and the current clinical application of MUC16 in ovarian cancer highlights their promise as therapeutics for glioma." (PMID 39767713, 2024).
renal cell carcinoma (4 papers, 2020 to 2024). "In contrast, transcription of the transmembrane glycoprotein, MUC15, whose loss is observed in certain tumours (including hepatocellular, prostate, and renal cell carcinoma) and during trophoblast invasion, was significantly downregulated (P < 10− 15)." (PMID 39483899, 2024). "Subsequently, we investigated the role and mechanism of MUC15 in promoting OS proliferation, migration and invasion, although a recent study of MUC15 reported a tumor suppressing role in renal cell carcinoma." (PMID 33391443, 2021). "MUC15, a subtype of the mucin family, can suppress tumor metastasis by inhibiting PI3K/AKT signaling in renal cell carcinoma." (PMID 34503278, 2021).
liver cancer (3 papers, 2021 to 2022). An epithelial or non-epithelial malignant neoplasm that arises from the liver. "Conversely, the formation of liver cancer was significantly reduced in MUC15-TG mice compared with that in WT mice." (PMID 35236826, 2022). "Conversely, MUC15 was downregulated in liver cancer and inhibited liver cancer metastasis by targeting EGFR/PI3K-AKT pathway." (PMID 34539882, 2021). "Moreover, our previous study demonstrated that MUC15 downregulation correlated with advanced stage, poor differentiation, and metastasis of liver cancer." (PMID 35236826, 2022). "Moreover, the mucin 15- (MUC15-) and MT1-MMP- (MMP14-) encoding genes are significantly related to capsule formation in liver cancer through the regulation of MMP2 expression." (PMID 34007838, 2021).
esophageal cancer (2 papers, 2020 to 2025). A primary or metastatic malignant neoplasm involving the esophagus. "Among 7 feature genes, MUC15 plays a role in a variety of tumors, but its role in esophageal cancer is unclear." (PMID 40225867, 2025).
gastric cancer (2 papers, 2020 to 2025). A primary or metastatic malignant neoplasm involving the stomach. "Therefore, we propose that an EMCN/MUC15 combination could be a potential prognostic signature for gastric cancer." (PMID 32175327, 2020).
influenza infection (2 papers, 2019 to 2021). "MUC15 is a cell surface protein that is believed to promote cell-extracellular matrix adhesion and it is implicated in affecting influenza infection, which may increase its relevance in the context of COVID-19 infection." (PMID 34616619, 2021). "Our study revealed that MUC15 was one of the few cell-surface mucins induced during influenza infection." (PMID 31307416, 2019). "While MUC15 did not interact directly with influenza virus, we showed that its increase coincides with the peak of immune activation and thus MUC15 may serve an immunomodulatory role during influenza infection." (PMID 31307416, 2019). "Therefore, in view of its consistent elevation across different hNEC samples and influenza strains, we assessed the effects of MUC15 changes following influenza infection." (PMID 31307416, 2019). "Nevertheless, in view of the strong induction of MUC15 following influenza infection of multiple strains, MUC15 may be exploited as a novel biomarker of influenza infection, and its functions during infection should be fully explored in the future." (PMID 31307416, 2019). "Correlations of MUC15 mRNA levels versus many immunological factors responding to influenza infection, have been revealed, and may be important for future studies to elucidate MUC15 immunomodulatory functions." (PMID 31307416, 2019). "Future work can therefore focus on the interaction between the influenza NS1 protein and MUC15, and as a possible diagnosticbiomarker for severe influenza infections." (PMID 31307416, 2019). "Quantitative real-time RT-PCR analysis of MUC15, MUC13 and MUC3A gene mRNA expression in hNECs infected with seasonal influenza H1N1, H3N2, and B, with uninfected control subjects as baseline (n = 4) and using PGK1 as the internal control." (PMID 31307416, 2019). "In addition, MUC1 is the first cell-surface mucin with anti-influenza function, and it was reported that MUC1 and MUC15 in the milk-fat globule membrane milk can limit bacterial and viral infections of the gastrointestinal tract." (PMID 31307416, 2019).
kidney cancer (2 papers, 2017 to 2023). Primary or metastatic malignant neoplasm involving the kidney. "We observed a general decrease in promoter methylation for mucins, which correlated with decreased expression of many genes, such as MUC15 in kidney cancers." (PMID 28978023, 2017).
melanoma (2 papers, 2008 to 2025). A malignant, usually aggressive tumor composed of atypical, neoplastic melanocytes. "We find that primary basal cell carcinomas, squamous cell carcinomas and thin melanomas express dramatically higher levels of many genes, including SPRR1A/B, KRT16/17, CD24, LOR, GATA3, MUC15, and TMPRSS4, than metastatic melanoma." (PMID 18442402, 2008).
ovarian carcinoma (2 papers, 2022 to 2024). A malignant neoplasm originating from the surface ovarian epithelium. "Our data indicates that HGSC patients with lower MUC15 have poorer overall survival and that MUC15 expression is lost during ovarian cancer progression." (PMID 39483899, 2024). "We identified the N-glycosylation of MUC15 and MUC20 in ovarian cancer cells; the potential of the MUC15 and MUC20 as the diagnosis marker remains to be investigated in the future." (PMID 36482940, 2022). "MUC15 was reported to participate in cell adhesion to the extracellular matrix in cancers, while MUC20 was reported to promote aggressive phenotypes in the epithelial ovarian cancer." (PMID 36482940, 2022).